HIF1A (hypoxia inducible factor 1 subunit alpha)
Diseases named in the same sentence as HIF1A in open-access papers (continued):
Sharing a sentence is not in itself a finding about the gene and the disease.
tumor (continued). "Tumor buds are known to express HIF-1a-mediated hypoxic tumor phenotype, degrade the underlying connective tissue stroma, and infiltrate the blood vessels/lymphatics." (PMID 38046721, 2023). "Tumors contain different proportions of intrinsically radioresistant cancer stem cell (CSC), which are closely associated with tumor hypoxia, and HIF-1α contributes to the development and maintenance of the CSC phenotype." (PMID 37226275, 2023). "Although [18F]FDG uptake cannot be considered a surrogate for tumor hypoxia, the expression of hypoxia-inducible factor-1 alpha (HIF1α) has been associated with [18F]FDG uptake." (PMID 36253663, 2023). "Results from a meta-analysis of eight clinical studies showed that HIF-1α overexpression correlated with a higher rate of lymph node metastasis, advanced tumor stage and was significantly associated with a poor outcome in PDACs." (PMID 36831579, 2023). "Collectively, these data indicate that specific HIF-1α deficiency in neutrophils decreased the glycolytic capability of neutrophils, leading to reduced tumor progression and improved survival of tumor bearing mice." (PMID 36614196, 2023). "Several reports found that the MDM2/HIF1α and NF-κB pathways were implicated in the pathological process of inflammation as well as tumor." (PMID 36673369, 2023). "Expression of HIF-1α were associated with tumour progression, poorly differentiated cells, histological type, tumour stage, lymph node metastasis, and poor survival." (PMID 37841777, 2023). "The tumor suppressor gene VHL mutation causes the loss of its ubiquitinated degradation of HIF‐1α, making stabilizing the level of HIF‐1α a key factor in treating cancer." (PMID 38131663, 2023). "BP-LCNs significantly downregulated the protein expression of survivin and hif-1α that are associated with tumor growth and metastasis, and upregulated the protein expression of p27KIP1, a modulator of apoptosis, in A549 cells." (PMID 37534226, 2023). "In-vivo studies confirmed that tumor growth is enhanced by HIF1a signaling, whereas its stable expression is linked with the restoration of tumor growth." (PMID 37858151, 2023). "Targeting HIF-1α alleviates the tumor-promoting effect of GSTZ1 deficiency in orthotopic mouse models of HCC." (PMID 37906252, 2023). "In particular, miR-21 has been shown to upregulate VEGF, TGF-β and HIF-1α at the post-transcriptional level, resulting in increased angiogenesis, which is associated with tumor growth and metastasis." (PMID 37108432, 2023). "MDA-MB-231 xenografts showed that cells expressing methylation-defective HIF-1α (K32A mutation) resulted in increased tumour formation, tumour weight and volume compared with the cells expressing HIF-1α WT." (PMID 35326563, 2022). "HIF-1α is also associated with genetic instability, tumor-promoting inflammation, and escape from immunity." (PMID 35681691, 2022). "Various clinical studies have approved that HIF-1α is significantly linked to cancer progression, assisting tumor invasion, metastasis, angiogenesis, and the development of resistance to various available cancer therapies." (PMID 35592530, 2022). "It was reported that, in tumor-associated fibroblasts (CAFs), HIF-1α activates the NF-κB signaling pathway causing an increase in the expression level of CCL5, which promotes tumor growth." (PMID 35682354, 2022). "Increased lactate dehydrogenase (LDH) levels are caused by the tumor’s increased glycolytic activity and tumor necrosis caused by hypoxia via HIF-1α." (PMID 36671699, 2022).
tumor (continued). "Carbonic anhydrase IX (CAIX), as the transmembrane protein with pH-regulatory effects, is a tumor-associated isoenzyme of carbonic anhydrases (CAs) family which is induced by HIF-1α under hypoxia and is rarely expressed in normal cells." (PMID 35413842, 2022). "Several studies have revealed that hypoxic exposure results in increased HIF-1α protein stabilization, which has been implicated in promoting the glycolysis of tumor cells." (PMID 36052242, 2022). "Loss of function or inhibition of pVHL expression prevents HIF-1α degradation, which supports tumor progression." (PMID 35565420, 2022). "In the hypoxic condition of tumor microenvironment, there is a repression of HIF-1α hydroxylation, associated with HIF activity." (PMID 35938170, 2022). "Loss of HIF-1α in NK cells blocks tumor growth and hypoxia upregulation of HIF-1α in NK cells is dependent on PI3K/mTOR signaling pathway activation in response to cytokine receptor gamma chain, reducing NK cells tumor suppressive function." (PMID 35211123, 2022). "High-dose hypofractionated radiation also causes vascular damage in tumors, thereby increasing tumor hypoxia and upregulation of hypoxia-inducible factors HIF-1α and HIF-2α, the master transcription factors for the cellular response to hypoxia." (PMID 35805044, 2022). "Overexpression of HIF-1α is highly associated in supporting tumor growth and metastasis by instigating angiogenesis and regulating cellular metabolism to overcome hypoxia." (PMID 36613878, 2022). "The hypoxia-inducible factor-1α (HIF-1α) pathway has been implicated in tumor angiogenesis, growth, and metastasis." (PMID 36558113, 2022). "In tumours, the hypoxia-inducing factor HIF1α has been implicated in the transcriptional regulation of βIII-tubulin via the 3′UTR of the TUBB3 gene and is thought to protect tumours against hypoxic injury." (PMID 35573698, 2022). "Overexpression of HIF-2α, compared to HIF-1α, was confirmed in TAMs found within primary invasive breast carcinomas, and was associated with a higher tumor grade." (PMID 35267567, 2022). "HIF-1α overexpression activates genes associated with tumor development and aggression and is associated with a poor prognosis." (PMID 36139362, 2022). "~70% of RCC patients exhibit deletions or loss-of-function mutations of the vhl gene, which is a tumor suppressor and functions as a ubiquitin E3 ligase of HIF1α and HIF2α proteins." (PMID 36284084, 2022). "Elevated HIF-1α levels are associated with tumor metastasis, poor patient prognosis and drug resistance." (PMID 35372052, 2022). "In brief, miRNA-210/155 and HIF-1α and 2α are considered master regulators of target genes implicated in increased tumor angiogenesis, metastasis, DNA repair, unstable tumor microenvironment (TME), and multidrug resistance." (PMID 35216330, 2022). "In the clear cell renal cell carcinoma microenvironment, glutamine consumption by the tumor cells causes the local depletion of extracellular glutamine, resulting in IL-23 secretion by tumor-infiltrating macrophages via the stimulation of HIF1α." (PMID 36233088, 2022). "Since HIF-1α is closely related to the key processes in tumor progression and its expression is also associated with patient survival, it is not surprising that targeting HIF-1α has been extensively studied as possible therapeutic strategy against cancers." (PMID 36532768, 2022). "Local tumor hypoxia is the leading cause of chemotherapy resistance, and hypoxia inducible factor-1α (HIF-1α) is the main hypoxia-induced transcription factor regulating the expression of chemoresistance-related genes." (PMID 35931669, 2022). "HIF-1α plays crucial roles in hypoxia-caused malignant transformation of tumor cells, as well as EMT and VM formation." (PMID 35309179, 2022). "HIF1α regulates macrophage function while HIF1α in tumor-associated macrophages support tumor growth." (PMID 36291563, 2022).
tumor (continued). "Targeting the HIF-1α/PD-L1 axis in tumor cells reactivated tumor-infiltrating lymphocytes and caused tumor rejection." (PMID 35239514, 2022). "This causes downregulated HIF-1α expression and alleviated tumor hypoxia, thereby increasing tumor sensitivity to Mn2+-induced CDT and TMZ-caused chemotherapy." (PMID 35710493, 2022). "HIF-1α decreases the susceptibility of cancer cells to T-cell-mediated cytotoxicity, contributing to tumor immune escape by increasing CTLA-4 expression on CD8+ T cells and PD-L1 expression on hypoxic cancer cells." (PMID 35493517, 2022). "Dis-regulated HIF-1α is often associated with altered expression of genes controlling angiogenesis, cell survival, and tumor invasion." (PMID 35069908, 2022). "HIF-1α activation leads to angiogenesis and tumor development, key features that are intrinsically linked to TSC." (PMID 36551683, 2022). "Tumour-associated hypoxia promotes the production of VEGF-A via hypoxia inducible factor 1α (Hif-1α), an important transcription factor that regulates angiogenesis, mainly through the induction of VEGF transcription." (PMID 36362718, 2022). "The direction of the effect of a variant HIF1A allele on tumour mass appears to be cancer type-specific." (PMID 34708297, 2022). "HIF-1α is crucial for myeloid cell-mediated inflammation and it has been demonstrated that tumor-associated macrophages (TAMs) also express HIF-2α under hypoxic conditions." (PMID 36496973, 2022). "Tumor angiogenesis is an important process for tumor growth and metastasis and is usually related to hypoxia, and HIF-1α is a master gene in mediating different hypoxia associated cell processes including tumor angiogenesis." (PMID 36347835, 2022). "HIF-1α overexpression in solid tumors is associated with tumor progression via a variety of processes, including proliferation, angiogenesis, invasion, and metastasis." (PMID 36080483, 2022). "Immunosuppressive cells including tumor-associated macrophages (TAMs) and myeloid-derived suppressor cells (MDSCs) are increased via HIF-1α signaling." (PMID 35747126, 2022). "Elevated HIF1A levels in several cancers have been associated with aggressive tumor progression, and thus has been implicated as a predictive and prognostic marker for resistance to therapy and increased mortality." (PMID 35252204, 2022). "Ingenuity Pathway Analysis revealed a link between GPx2 loss, tumor angiogenesis, metabolic modulation, and HIF1α signaling." (PMID 35193955, 2022). "IL-4, IL-10, and IL-13 signaling, along with significantly elevated tumor-associated transcription factor abnormalities, upregulation of IL-17 and Hif-1a pathways, and glucose metabolism pathway, was enriched in Mac3, which pointed to M2 characteristics." (PMID 35874770, 2022). "HIF-1α is critical for cellular adaption under hypoxic conditions and is often associated with tumor progression and survival." (PMID 35494068, 2022). "HIF-1α, a major transcription factor, has been reported to be associated with radiation-mediated hypoxia and is a major determinant of tumor radiosensitivity." (PMID 36418890, 2022). "Tumor cells grow under conditions of relative oxygen deficiency because: (i) oncogenic activation forces glucose uptake; (ii) hypoxia stabilizes HIF1α; and (iii) tumor cells compete with stromal cells for oxygen, leaving them in a hypoxic state." (PMID 35053485, 2022). "The transcription factor HIF-1α plays a major role in regulating these processes, and has been linked to tumor survival, progression, and chemotherapy resistance in PDAC22–24,26,27." (PMID 35440539, 2022). "Tumor hypoxic stress causes HIF-1α to mediate the secretion of a variety of immune evasion-promoting molecules from tumor cells, including TGF-β, VEGF, IL-10, and PGE2." (PMID 36233088, 2022). "Gal‐3 is also expressed in tumor tissues in a HIF-1α-dependent manner, causing an increase in PD‐L1 level via STAT3 phosphorylation in carcinomas." (PMID 36071472, 2022).
tumor (continued). "It is also well established that overexpression of HIF1α is associated with OVCA tumor aggressiveness, progression, and metastasis, but inhibition of HIF1α as a therapeutic option has not been successful." (PMID 36291171, 2022). "Glutamine deprivation in the TME, induced by glutamine-addicted tumor cells, promotes IL-23 expression on Tumor-Associated Macrophages (TAMs) through HIF-1α activation, which is related to higher IL-10 and TGF-β production and recruitment of Tregs." (PMID 36713558, 2022). "Colegio and colleagues demonstrated that tumor-derived lactate acts to polarize tumor-associated macrophages in an M2 profile by impacting the expression of HIF1-α." (PMID 36033972, 2022). "A concomitant increase in HIF-1α expression and TAMs in tumor tissue was identified as an independent risk factor for poor prognosis." (PMID 35681691, 2022). "Numerous studies believe that HIF-1α acts as a risk factor for determining tumor prognosis and a vital antitumor target." (PMID 35528614, 2022). "HIF-1α loss of function results in decreased tumor growth, vascularization, and metastasis, whereas HIF-1α gain of function has the opposite effects." (PMID 36230617, 2022). "The hypoxic microenvironment caused by high tumor metabolism in various solid tumors leads to increased HIF-1α expression." (PMID 35931669, 2022). "HIF-1α, a key hypoxia-inducible transcription factor, is associated with tumor development as it functions as a master regulator of genes involved in angiogenesis, glucose metabolism, and other cellular pathways." (PMID 35198082, 2022). "The activation of JAK/Stat signaling is associated with the establishment of the tumor microenvironment, and Stats play important roles in regulating the stability of HIF-1α proteins." (PMID 36230633, 2022). "In another study, high tumour HIF-1α and HIF-2α levels were both associated with sensitivity to sunitinib with better clinical response." (PMID 36551652, 2022). "Due to their accelerated growth rate, many malignant tumours are subject to hypoxia, which promotes angiogenesis via induction of pro-angiogenic factors i.e., HIF-1α and angiogenesis-associated factors (AAFs)." (PMID 35276890, 2022). "Studies have shown that upregulation of HIF-1α activity promotes tumor-associated angiogenesis, thereby promoting tumor cell survival and proliferation in solid tumors." (PMID 35664561, 2022). "HIF-1α is the master regulator of the glycolytic phenotype and is caused by hypoxia or by aerobic glycolysis observed in many tumor cells." (PMID 36010843, 2022). "In this analysis, HIF-1α expression is significantly associated with poor tumour differentiation, higher proliferation index, presence of necrosis and lower MVD." (PMID 36233825, 2022). "According to reports, HIF-1α expression is abnormally elevated in some malignancies, suggesting that HIF-1α expression is associated with tumor genesis, progression, and poor prognosis." (PMID 35664561, 2022). "First, tumor-associated hypoxia caused by hypoxia-inducible factor 1-α (HIF1-α) promotes PD-L1 expression on the surface of tumor-infiltrating MDSCs, which inhibits T cell function by binding to PD-1 expressed on T cells." (PMID 36146572, 2022). "Previous reports have associated the expression of HIF-1α and its target genes with immunosuppressive functions in the tumor microenvironment." (PMID 36496973, 2022).
tumor (continued). "In CRC, for example, LRG1 has been shown to inhibit apoptosis and modulate the EMT of tumour cells through expression of the transcription factors RUNX1 and HIF-1α, whose association with TGFβ and contribution to tumour growth are well-established." (PMID 35062948, 2022). "Numerous studies have demonstrated that the HIF-1α-mediated activation of autophagy causes chemo/radioresistance in tumor cells." (PMID 36551540, 2022). "In glioblasts, PINK1 can negatively regulate the growth of tumour cells, and the loss of its expression can stabilize HIF1a and then induce the production of ROS and tumour growth." (PMID 36200262, 2022). "Because data on the SNP’s functional consequences are scant, we studied HIF1α expression by immunohistochemistry in tumour samples from major and minor allele carriers." (PMID 34708297, 2022). "In contrast, lactate signaling in tumor cells increases glucose uptake, enhances expression and activity of glycolysis enzymes and reduces mitochondrial function via a mechanisms linked to HIF-1α and PIK3CA." (PMID 35693822, 2022). "An analysis of 10 HCC patients revealed that the protein expression of STIM1 and HIF-1α was positively correlated in patient tissues and was also associated with the tumour size in a xenograft mouse model." (PMID 35269437, 2022). "HIF-1α, for example, can recruit myeloid-derived suppressor cells, regulatory T-cells, tumour-associated macrophages with immunosuppressive properties, as well as limit cytotoxic T-lymphocyte invasion." (PMID 35432450, 2022). "Adenosine A2a receptor (A2AR) expressed on tumor cells inhibits the activation of immune cells and its expression is associated with cytokines such as HIF-1α." (PMID 36532071, 2022). "The reported cadherin switch, and expression of EMT-associated transcription factors TWIST-1, ZEB-1, and HIF-1α were highly indicative for EMT events in the tumor, possibly explaining the metastatic behavior." (PMID 35215208, 2022). "To address this, we first compared the effects of pharmacological HIF-1α inhibition with LEM on tumor growth rate in mice sufficient or deficient in adaptive immunity." (PMID 35239514, 2022). "VEGF overexpression has been shown to be driven by specific genetic mutations, by HIF-1α under hypoxic conditions, or through autocrine secretion in the tumor microenvironment." (PMID 35910247, 2022). "Loss of myeloid HIF-1α results in impaired myeloid cell infiltration and inflammation and decreased tumor progression in a spontaneous mammalian breast cancer model." (PMID 34054802, 2021). "Secretion of VEGF-A facilitated by the ROS/HIF-1α axis was shown to cause resistance to etoposide and doxorubicin, presumably via mechanisms related to improved vascular stability of the tumour." (PMID 34829672, 2021). "Further, bioinformatics STRING databases strongly indicate the liaison of HIF-1α, HK 2, and Hsp70 in a network of closely linked cooperative molecules involved in regulating tumor metabolism and survival." (PMID 33716751, 2021). "Meanwhile, HIF-1α was reported to enhance TAM (tumor-associated macrophages)-mediated T cell function suppression and promote tumor progression." (PMID 33754005, 2021). "These researchers found that tumour associated macrophages (TAM) produce extracellular vesicles (EV) which contain HIF-1α-stabilising long-noncoding-RNA (HISLA)." (PMID 33807045, 2021). "The study revealed that HIF1α was primarily expressed in tumor-associated macrophages (TAM), whereas HIF2α and HAF were mainly expressed in tumor cells." (PMID 34384473, 2021).